BTK (Bruton tyrosine kinase)
Diseases named in the same sentence as BTK in open-access papers (continued):
Sharing a sentence is not in itself a finding about the gene and the disease.
tumor (continued). "This is directly addressed with immuno‐oncology drugs, but even drugs such as BTK inhibitors which have previously focused on B‐cell effects in WM can have broader ramifications and potential efficacy outside of the on‐target tumour activity." (PMID 41447345, 2025). "BTK inhibitors selectively suppress the kinase activity of BTK, a mechanism that effectively reduces the growth and spread of hematologic tumor cells." (PMID 41164126, 2025). "Our patient was treated with zanubrutinib, a BTK inhibitor, which resulted in significant IgM reduction and tumor shrinkage." (PMID 41346800, 2025). "R406 (BRK inhibitor) and ACP196 (BTK inhibitor) showed little anti-tumor effect alone or together with GEM." (PMID 40859234, 2025). "Previous studies have also found that anlotinib can promote tumor cell apoptosis through Erk, BTK, PI3K/AKT/mTOR signaling pathways." (PMID 39193386, 2024). "It has been described that BTK not only plays important roles in hematopoietic cells but also mediates relevant processes in the tumor microenvironment, rendering BTK an interesting and actionable target for treating solid tumors." (PMID 38790974, 2024). "In comparison, JeKo-1 tumors with low sensitivity to BTK inhibition yielded qualitatively similar results, although the changes in lactate, alanine, and tumor growth inhibition were much less robust and less statistically significant." (PMID 38965536, 2024). "The effect of BTK inhibition on tumor growth was confirmed by immunostaining of resected tumors from IBR-treated vs. drug vehicle-treated mice for cell proliferation-associated Ki-67 protein." (PMID 38965536, 2024). "Pre-treatment with BTK inhibitors reduces tumor size, decreases burden, and maintains a healthy immune microenvironment." (PMID 39026380, 2024). "Recently, researchers have introduced pirtobrutinib, a reversible, noncovalent BTK inhibitor that is highly selective and effectively inhibits BTK phosphorylation, cellular proliferation, and tumor growth." (PMID 39777345, 2024). "By targeting the multifaceted functions of BTK and its interplay with the tumor microenvironment, researchers strive to optimize therapeutic strategies and improve outcomes for patients with B-cell malignancies." (PMID 39062757, 2024). "BGB-16673 exposure increased with dose, and preliminary pharmacodynamic data showed significant reductions in BTK protein levels in both peripheral blood and tumor tissue." (PMID 39062757, 2024). "We found that there was a predominance of high expression (≥ 2 scoring) both of the tumor cells (n = 67) and tumor vasculature (n = 49) compared with known high BTK expressing lymph tissue and low expressing BTK seen in liver, colon, lung and soft tissue." (PMID 38589905, 2024). "Biologically, BTK inhibition interferes, within the tumor microenvironment, with different pathways required for CLL cell survival and proliferation such as the B-cell receptor (BCR), integrins and cytokines/chemokines receptors." (PMID 38914716, 2024). "Preliminary data from a phase 1 trial (NCT05006716) of 26 patients, with at least 2 previous lines of treatment, showed substantial reductions in BTK protein levels in peripheral blood and tumor tissue, even at the lowest dose." (PMID 39456530, 2024). "Upon preliminary pharmacodynamics (PD) data analysis, we observed that BTK protein levels in tumor tissue as well as in peripheral blood are significantly reduced even at the lowest dose." (PMID 39169396, 2024).
tumor (continued). "While second-generation BTK inhibitors have shown better BTK selectivity and less off-target toxicity, they cannot reverse the resistance of tumor cells to ibrutinib." (PMID 39777345, 2024). "The anticancer drug ibrutinib (IB), also known as PCI-32765, is a compound that irreversibly inhibits Bruton’s tyrosine kinase (BTK) and was initially developed as a treatment option for B-cell lineage neoplasms." (PMID 37111671, 2023). "In conclusion, tirabrutinib exerted an anti-tumor effect by regulating multiple BTK downstream signaling proteins, such as NF-κB, AKT, and ERK, in ABC-DLBCL." (PMID 36897912, 2023). "Tumor-infiltrating lymphocytic B cells program macrophages to the M2 phenotype via Bruton tyrosine kinase (BTK) activation in a PI3K-Y manner and inhibit B-cell infiltration." (PMID 36816959, 2023). "To better simulate the complex tumor microenvironment (TME), we next tested the effects of BTK inhibition on the EMT in three-dimensional (3D) cultures of HNSCC tumor cells, employing the sphere formation assay on ultra-low attachment (ULA) surface plates." (PMID 37685940, 2023). "The contradiction of the clinical effects of BTK inhibitors in tumor therapy proves that BTK plays a heterogeneous and complex role in the development of different types of tumors." (PMID 37638060, 2023). "Anti-tumor strategies such as BTK inhibitors and immune checkpoint inhibitors were combined to enhance the effects of CAR-Ts." (PMID 37298069, 2023). "Some non-clinical studies have shown the anti-tumor effect and anti-tumor mechanism of BTK inhibitors in ABC-DLBCL cell lines." (PMID 36897912, 2023). "UBX-382 is another novel BTK degrader that inhibits both wild-type and BTK mutant tumor growth in DLBCL via targeting the BCR pathway." (PMID 37626420, 2023). "There were also studies that used other anti-tumor drugs, such as BTK inhibitors and immune checkpoint inhibitors, which can enhance the efficacy and activity of CAR-Ts." (PMID 37298069, 2023). "Together, our in vitro and in vivo data suggest the abrogation of BTK expression or its activity in patients with HNSCC as a powerful treatment option to suppress tumor growth as well as tumor induced angiogenesis." (PMID 36612306, 2023). "Taken together, these results indicate that in this model, tirabrutinib exerted anti-tumor effects in response to BTK inhibition." (PMID 36897912, 2023). "Several previous studies have shown that BTK has a certain role in promoting tumor occurrence and development." (PMID 37638060, 2023). "This work defines a new axis comprising BTK and β-catenin, which partakes in the cross-talk between tumor cells and the microenvironment and that can be targeted by ibrutinib." (PMID 38139452, 2023). "In contrast to the resistance of the tumor organoids to chemotherapy drugs, multiple targeted agents showed good to exceptional activity, including the BTK inhibitor, ibrutinib (SPM score 97.3) and the EGFR inhibitor, afatinib (SPM score 95.9)." (PMID 37202426, 2023). "Ibrutinib targets the B-cell receptor pathway and immune cells in the tumor microenvironment via BTK, as well as kinases relevant to solid tumor treatment, including tyrosine kinase ETK/BMX and interleukin-2–inducible T-cell kinase (ITK)." (PMID 37296940, 2023). "More importantly, the expression of the BTK gene is also significantly related to the patient's age, gender, tumor range (T), lymph node invasion (N), tumor stage, and prognosis, and its expression level gradually decreases with the progress of the disease." (PMID 37638060, 2023). "We have recently shown that both oncogenic BTK isoforms, BTK-p80 and BTK-p65, coexist in tumor cells of the head and neck origin." (PMID 37685940, 2023). "To further evaluate the effect of ibrutinib on BTK phosphorylation in TIL-Bs, we performed mIHC and confirmed the inhibition of BTK phosphorylation in the TIL-Bs of ibrutinib-treated tumor samples." (PMID 37190284, 2023).
tumor (continued). "The interpretation of these data is rather intricate, since BTK is highly expressed in tumor infiltrating B and innate immune cells." (PMID 36612306, 2023). "BTK KD in the JeKo-1 cells showed comparably decreased tumor cell presence in the spleen (P < 0.001) and BM (P < 0.001), which was also seen with MALT1-KO cells." (PMID 36719376, 2023). "In summary, the highly selective BTK inhibitor tirabrutinib exerted an anti-tumor effect via the regulation of multiple BTK downstream signaling proteins, such as NF-κB, AKT, and ERK, in ABC-DLBCL cell lines." (PMID 36897912, 2023). "Our findings demonstrate that chemical or genetic abrogation of BTK activity leads to inhibition of tumor progression in terms of proliferation and vascularization in vitro and in vivo." (PMID 36612306, 2023). "Multiple mechanisms responsible for the resistance of BTK inhibitors include mutations in BTK and downstream signaling molecules, such as PLCγ2, CARD11, and BCL10 leading to prolonged and BTK-independent NF-κB activation resulting in tumor cell growth." (PMID 37845755, 2023). "Abrogation of BTK activity inhibited tumor progression in terms of proliferation and vascularization in vitro and in vivo in our previous study." (PMID 37685940, 2023). "As a novel BTK inhibitor, Tirabrutinib exerts its anti-tumor and anti-inflammatory effects through selective inhibition of BTK activity." (PMID 38138527, 2023). "Inhibition of tumor growth by BTK inhibition was most effective in DLBCL PDX models of the ABC subtype." (PMID 37989777, 2023). "The reduced vascularization documented on in vivo tumor xenografts is in line with the in vitro impaired VEGF A secretion upon BTK inhibition." (PMID 36612306, 2023). "It was found that tumor tissues had lower expression of BTK and DPEP2 at mRNA and protein levels compared to normal tissues." (PMID 36991102, 2023). "Treatment with the BTK inhibitor AVL-292 also reduced tumor sphere formation in HNSCC-derived cell lines and the expression of the stemness marker ALDH1A1." (PMID 37685940, 2023). "Currently, downstream BCR signaling molecules (PKD2 or BTK), tumor cell-derived IL-18 cytokine, and Breg-cell-mediated IL-35 are utilized to target pro-tumorigenic suppressor B cells in PDAC." (PMID 37033931, 2023). "Although the direct effects on BCR signaling pathways are well recognized, the pleiotropic implications of BTK inhibitors on the overall tumor microenvironment are only just beginning to be comprehended." (PMID 36903645, 2023). "On the other hand, ibrutinib’s off-target inhibition of JAK3, ITK, and EGFR means that it can target oncogenic pathways other than BTK in tumor cells and act as a T-cell modulator in combination immunotherapy." (PMID 36903645, 2023). "Similar to other conclusions, tumor burden was further reduced when the Pim kinase inhibitor was given as dual therapy with ibrutinib, an inhibitor of Bruton’s tyrosine kinase (BTK)." (PMID 36694243, 2023). "BTK is widely expressed in cells of haematopoietic origin, which are pivotal components of the tumour microenvironment." (PMID 36138486, 2022). "Among other cells of the tumor microenvironment expressing BTK, we can find monocytes and mast cells." (PMID 35456016, 2022). "BTKi achieves its anti-tumor effects by inhibiting BTK activation and blocking a series of malignant transformations in B-cell tumors." (PMID 36325357, 2022). "ASK120067 reduced the activation of BTK in tumor tissues, which suggested a correlation between the anti-tumor potency and target-inhibition activity of ASK120067." (PMID 36588692, 2022). "Ibrutinib, a first in class BTK inhibitor reduced tumor burden in 7 out of 9 patients with R/R MCL in a phase I study." (PMID 34821081, 2022). "We, therefore, tested a drug library on the three tumor organoid models that contained small molecules against a wide range of cancer‐associated pathways, that is, EGFR, MAPK, BTK, and PI3K/mTOR." (PMID 35993110, 2022).
tumor (continued). "IBR is a Bruton’s tyrosine kinase (BTK) inhibitor, and BTK is overexpressed on TAMs.The nano-system delivered IBR to the tumor microenvironment efficiently and significantly reduced tumor growth." (PMID 36559202, 2022). "BTK and its family kinases are involved in immune tolerance, creation and regulation of tumor microenvironment, and tumor immune-escape mechanisms." (PMID 36294458, 2022). "BTK inhibitors disrupt these amplification cycles by disrupting tumor cell-microenvironment interactions." (PMID 35883678, 2022). "BTK, SYK, and HLA-DRB5 were only highly expressed in PH024, and BTK is a small-molecule inhibitor which exhibited impressive anti-tumor activity in clinical studies in patients with various B-cell malignancies." (PMID 35865544, 2022). "The synthetic SA/IBR/EPG selectively delivered IBR to TAMs and blocked BTK activation, thus inhibiting Th2 tumor-promoting cytokine release and reducing tumor volume and angiogenesis." (PMID 35701781, 2022). "BTK inhibitors target cell homing, signaling, maturation, and survival in tumor microenvironments, resulting in apoptosis of cells in B-cell malignancies." (PMID 36294458, 2022). "Taken together, our studies demonstrated that ASK120067 exerted preclinical anti-tumor activities against B-/T-cell malignancy by targeting BTK/ITK." (PMID 36588692, 2022). "Oral administration of SHP-1 agonist showed the potent anti-tumor effects compared to a selective Bruton’s tyrosine kinase (BTK) inhibitor ibrutinib in mice bearing U2932 xenografts." (PMID 35941532, 2022). "BTK is overexpressed in > 85% of tumor cells and can increase the stemness properties of cancer cells from MM patients, including self-renewal, clonogenicity, and drug resistance." (PMID 36183125, 2022). "Pirtobrutinib’s reversible binding, selectivity to BTK, high potency, desired pharmacological profile, and favorable clinical outcome in patients with WT or mutant BTK suggested potency of this agent for any BTK-driven tumor." (PMID 35595730, 2022). "Consistently, expression of p-BTK in tumor tissues in mice in the 25-mg/kg group decreased 21 days after ASK120067 treatment." (PMID 36588692, 2022). "In vivo BTK inhibition abolished tumor formation, while BTK overexpression increased cancer incidence and overall mortality." (PMID 35159041, 2022). "The results also indicated that gene sequencing of tumor specimens can help to screen the patient population responding to BTK inhibitor targeted therapy." (PMID 35785180, 2022). "Several studies assessed the role of the TME interactions with the tumor B cell in this context, and subsequently the impact of BTK inhibitors." (PMID 35804999, 2022). "This is due to BTK’s robust expression in MM cells and its effect on both the tumor, stem cells and BMM." (PMID 34071917, 2021). "B-cell receptor (BCR) antagonists such as the BTK inhibitor ibrutinib have proven to effectively target chronic lymphocytic leukemia (CLL) tumor cells, leading to impressive response rates in these patients." (PMID 33627156, 2021). "The function of the low-expression group of BTK was mainly enriched in amino acid metabolism, base excision repair and some typical tumor pathways produced by proteins." (PMID 34805160, 2021). "Myeloid-derived suppressor cells (MDSC), another type of tumor-promoting myeloid cells, express BTK and it has been shown that ibrutinib blocks their development and immunosuppressive function." (PMID 34276674, 2021). "This agent inhibited angiogenesis, Th2 tumorigenic cytokine secretion, and tumor progression and represents a promising targeted approach for targeting BTK in TAM." (PMID 33818636, 2021). "Myeloid cells are crucial components of the tumor microenvironment and suppressive myeloid cells contribute to cancer progression, highlighting a potential role for BTK inhibition in the treatment of malignancy." (PMID 33818636, 2021).
tumor (continued). "In spite of many signaling pathways found in the tumor microenvironment necessary for tumor cell proliferation and survival, the BTK signaling pathway is arguably one of the most vital signaling pathways for cancer progression." (PMID 34063667, 2021). "Antibody-mediated depletion of CD8+ T-cells reversed the anti-tumour effect of the BTK inhibitor and thus underscored the importance of CD8+ T cells for this therapeutic strategy." (PMID 34439389, 2021). "In conclusion, this report demonstrates that BTK is highly expressed in both M-MDSCs and G-MDSCs isolated from mice bearing NB tumors as compared to MDSCs isolated from non-tumor-bearing mice." (PMID 33669187, 2021). "Although BTK is most well-known for its function in B cell maturation and processes necessary for cellular homeostasis, its contribution to tumor progression by activating cells known for their pro-tumor properties is also well documented." (PMID 34063667, 2021). "Further, data in the GEPIA database were verified, and results confirmed the low expression of BTK and Cd1c in LUAD tumor tissues, and the finding that patients with high expression of BTK or Cd1c survived longer." (PMID 34805160, 2021). "We found that BTK is the proposed kinase for five of the most abundant peptide substrates in GBM tumour tissues relative to tumour cell lines." (PMID 34645618, 2021). "In this review, we summarize the latest findings of the BTK signaling in the tumor microenvironment of the solid tumors and its potential use for treating solid tumors." (PMID 34063667, 2021). "Here, we review BTK signaling within the cells found in the tumor microenvironment as well as summarizing clinical trials using BTK inhibitors which target the tumor microenvironment in an attempt to combat solid tumors." (PMID 34063667, 2021). "The potential effects of BTK inhibition on the tumor microenvironment and the potency of immune-checkpoint inhibitors will be clarified in part by the ongoing clinical trials that combine BTK inhibition with immune checkpoint blockade." (PMID 33937249, 2021). "This study has shown that BTK is expressed in MDSCs isolated from tumor-bearing hosts, and ibrutinib alters the functions of MDSCs, including NO production and migration." (PMID 33669187, 2021). "The use of specific inhibitors targeting the tumor cell survival dependency on key signaling proteins (BTK, Pi3K) has proven its efficacy in clinics, however mutations in elements of these pathways ultimately lead to tumor resistance and escape." (PMID 33833385, 2021). "In PK/PD studies, the irreversible binding of SY-1530 to BTK was detected in peripheral blood mononuclear cells, thus indicating that SY-1530 suppresses tumor growth through inhibiting BTK." (PMID 34264564, 2021). "Bruton tyrosine kinase (BTK), a key B cell and macrophage kinase, contributes to the regulation of T cell-dependent anti-tumor immune responses in PDA." (PMID 34290984, 2021). "BTK in paracancerous tissues was significantly higher than that in tumor tissues, which was consistent with the results in the TCGA and GEO." (PMID 34805160, 2021). "Overall, BTK inhibition has shown a favorable benefit in solid tumors with anti-tumor activity; however, these data are still preliminary, and it is possible that these effects are a result of the off-target effects of BTK inhibitors on other kinases." (PMID 33818636, 2021). "Previously, it has been demonstrated that BTK plays an important role in the development of tumours via activation of antiapoptotic pathways." (PMID 33522320, 2021). "A comprehensive outline of how BTK interacts in each of these pathways and the implications it has in neoplasm is provided below." (PMID 34071917, 2021). "For instance, ibrutinib influences tumor cells by inhibiting Bruton tyrosine kinase (BTK); it also has off-target effects on Tec protein tyrosine kinase (TEC)." (PMID 34869670, 2021).